IL1A (interleukin 1 alpha)
Diseases named in the same sentence as IL1A in open-access papers (continued):
Sharing a sentence is not in itself a finding about the gene and the disease.
tumor (continued). "HPV infection appears to ablate the ability of keratinocytes to express IL-1β; indeed we previously observed low levels of IL-1α and IL-1β in HPV-positive compared to HPV-negative cell lines and tumour biopsies." (PMID 35047989, 2021). "In our study, we demonstrated that IL1α stimulated by FABP4 knockdown takes the main responsibility of macrophages phenotype skewing and anti‐tumor ability." (PMID 33931964, 2021). "The expression of IL1R1 in the tumor microenvironment, the main receptor of IL1α and β, due to the interconnection with the NF-KB and MAP kinase pathways, plays contrasting roles in different tumor stages." (PMID 34073987, 2021). "Upon combination therapy, we observed a significant increase in IL1α and IL1β protein levels in the TME, both correlating with tumor regression." (PMID 34446712, 2021). "In the tumor stage contrasts for STAD and COAD, we see Th2 and NK cells expressing inflammation related genes IL1A, IL1B, IL4, and TNF." (PMID 34512714, 2021). "The membrane-bound IL-1α exhibits a mainly immunostimulatory activity, while IL-1β in the TME exhibits a pro-inflammatory role in tumorigenesis and tumor-invasion-promoting activity, as well as immunosuppressive activity." (PMID 33557173, 2021). "Among the inflammatory mediators, cytokines IL-1α, IL-1β, IL-6, and IL-8 and chemokine CXCL10 were highly expressed, suggesting a function of CAFs in tumor-mediating inflammation." (PMID 34298873, 2021). "The secretion of IL1A and IL6 in the serum of patients with higher HIF1α mRNA expression was significantly higher than the patients with lower HIF1α mRNA levels in tumor samples." (PMID 34362882, 2021). "PD-L1 expression in tumor cells is induced by a variety of growth factors including INF-γ, IL-1α and IL-27." (PMID 34299131, 2021). "To explore the mechanism by which hypoxia elicits inflammation in lung tumors, we studied IL1A and IL6 expression in tumor cells and macrophages in response to hypoxic stress." (PMID 34362882, 2021). "Screening for tumor‐related cytokines, such as TNF‐a, VEGF, bFGF, IL‐1α, and IL‐6, as suggested by previous studies, was performed by an ELISA of collected serum." (PMID 33112032, 2021). "The suppression of exosomal miR101 stimulates the expression and secretion of IL1A and IL6 in macrophages and leads to inflammation in the tumor microenvironment." (PMID 34362882, 2021). "Pro-inflammatory cytokines such as IL-1α, IL-1β, IL-6, TNF-α were constitutively expressed in tumor microenvironment to facilitate carcinogenesis." (PMID 34379689, 2021). "Among the candidate list we identified (MMP10, IL1α, TIE1, FGF2, BMP6), IL1α has been reported to be released by both stromal cells and PC cells, and to promote tumor growth in PDAC." (PMID 33105540, 2020). "IL1A is an inflammatory cytokine, while TDO2 is involved in a pathway potentially suppressing anti-tumor immune responses." (PMID 32290493, 2020). "Tumor supporting cytokines are released from tumor and stromal cells upon AT1 receptor activation via Ang II including, TGF-β and Interleukins (IL-1α, IL-1β, IL-6, IL-8)." (PMID 32503281, 2020). "Cytokines such as IL-1α and chemokines (MIP-1α) by tumour and immune cells is particularly involved in the recruitment of immune cells at the tumour site." (PMID 32560253, 2020). "We found that these receptors are highly correlated to the innate and adaptive immunity-related cells, as well as IL-10, IL-6, CXCL10, CCL2-CCL5, TGFB1 in KIRC tumors, whereas in KIPRP tumor tissues IL8, IL1A, and TNF were highly correlated." (PMID 33330620, 2020). "Co-culture of BMDM with tumour cells led to increased expression of iNOS and CD206, and Il1α, Il1β, Il6 and Tgfβ in the BMDM." (PMID 32792542, 2020). "SW480- and U87-MG-derived exosomes induce the release of IL-1α, IL-8 and MCP-1 by monocytes, while exosomes released from all tumor cell lines after LPS treatment trigger the production of IL1β, IL-10, IL-6, MIP-1α, MIP-1β and TNF-α cytokines." (PMID 31186484, 2019).
tumor (continued). "Based on the intersection of interleukin superfamily signature between human BC tissues and cell lines to exclude the tumor heterogeneity, both TNBC tissues and cell lines dominantly expressed IL1A, IL1B, IL8, and IL32." (PMID 30728901, 2019). "IL-1α activated and untreated BPH-1 cells were injected into SCID mice and tumor growth was monitored." (PMID 29502208, 2018). "Like NK cells, T cells can be mobilized, activated, and differentiated in the senescent tumor from a variety of SASP factors including CCL27, CCL2, CCL5, CXCL11, and IL-1α." (PMID 29868482, 2018). "The end targets of these pathways, including cytokines (IL1A/B, IL6, IL8, IL18) and genes related to cell proliferation (JUN, SRF), were upregulated, suggesting that the activation of these TLRs leads to tumor growth." (PMID 29912993, 2018). "Mice with tumors had elevated levels of inflammatory cytokines including IL-1α, IL-6, MIP-1α and G-CSF and lower levels of TNFα and CXCL1 compared to non-tumor bearing mice (all p < 0.05; statistics are provided in S1 Table)." (PMID 30532184, 2018). "The delay in tumor growth was accompanied by a reduction in angiogenesis as measured by determining the number of blood vessels present in IL-1Ra treated and control tumors, suggesting that IL-1α pathway enhancement of tumor growth may due to increased angiogenesis." (PMID 29502208, 2018). "Numerous studies have indicated that tumor cells exhibit constitutive production of TNF-α proinflammatory cytokines, IL-1α, IL-6, and GM-CSF (macrophage-granulocyte colony-stimulating factor)." (PMID 28785138, 2017). "While also pleiotropic in its effects, IL-1α can serve to costimulate CD8+ T cells and enhance antigen presentation by tumor cells." (PMID 28932226, 2017). "Functionally, we show that NEDD4-mediated H3 ubiquitination, by transcriptionally activating IL1α, IL1β and GCLM, is important for tumour sphere formation." (PMID 28300060, 2017). "Target genes of glucose-induced H3 ubiquitination, such as interleukin (IL)-1α, IL1β and glutamate-cysteine ligase regulatory subunit (GCLM), are also important factors for tumour sphere formation." (PMID 28300060, 2017). "Employing this approach, they recognized a core of nine cytokines that consistently correlated with efficacious tumour suppression: IL-12p70, IFN-γ, IL-1α, IL-1β, IL-2, IL-3, IL-6, CXCL10, and CXCL9." (PMID 29089667, 2017). "Within the molecules that are increased in the tumor microenvironment, glutamate and immune factors such as TNF-α, IL-1α, and CCL2 should be taken into special consideration." (PMID 29163208, 2017). "We have reported that the augmented expression of IL-1α, IL-1β, VEGF-A and VEGF-C by macrophages promotes tumor growth and tumor angiogenesis/lymphangiogenesis." (PMID 26778110, 2016). "Our study points to the production of soluble cytokines IL1A, IL1B and IL8, as markers of a poor response to cetuximab and as potential key factors in CRC tumor adaptation to cetuximab pressure." (PMID 27708224, 2016). "In accordance with our in vitro data, IL1A, IL1B and IL8 were overexpressed in tumorgrafts that proved to be resistant to EGFR blockade (tumor volume increase of at least 35% compared to the initial, pre-treatment volume)." (PMID 27708224, 2016). "Cytokines, such as TNF-α, IL-1α, IL-1β, IL-6, and TGF-β, are produced by tumor cells and tumor-infiltrating lymphocytes and can greatly influence cellular radiosensitivity and the onset of tissue complications." (PMID 26569225, 2015). "When type 2 cells are introduced into mice, their production of TNF-α, IL-1α, or CCL5 is expected to induce the production of cytokines such as IL-6 and IL-8 in the associated fibroblast-like cells, which might in turn function as paracrine factors in tumor formation." (PMID 25673149, 2015). "Again both, IL-1α release and DC activation, were strictly dependent on RIPK3 expression in the tumor cells." (PMID 25888634, 2015).
tumor (continued). "This is despite the fact that tumor incidence and the nature of the local inflammatory response were comparable in 3-MCA-treated IL-1α−/− mice and WT mice." (PMID 23847618, 2013). "We have demonstrated that the p38MAPK signaling pathway is involved in the expression of IL-1α by PDAC cells and that IL-1α initiates a change in the PDAC phenotype and properties, making the tumor cells more prone to migrate." (PMID 23951028, 2013). "M2-like TAM have high levels of mannose receptor-1 (MRC1/CD206), arginase-1 (Arg1), IL-10 and chemokines CCL22 and CCL17, whereas anti-tumor M1-like TAM express high interferon (IFN)γ and IL-1α/β levels; TNFα marks both M1- and M2-polarized TAM." (PMID 24317954, 2013). "The protein profiles of nine targets, namely IGFBP2, IGF1, SHKBP1, ETS1, IL1α, STX2, MAML3, EGR3 and XIAP were verified as significant contributors to tumor classification." (PMID 24282616, 2013). "In this model, IL-1α-induced IL-6 activates STAT3 and promotes liver regeneration and tumor outgrowth." (PMID 23847618, 2013). "We have previously shown that the IL-1α positive PDAC cell lines secrete IL-1α protein and this is in accordance with findings from other tumor cell lines." (PMID 23951028, 2013). "The most important findings suggested that IGF1, IL1α, SHKBP1, and EGR3 were able to distinguish between controls and primary tumor-bearing patients." (PMID 24282616, 2013). "As IL-1α, IL-2, IL-6, TNF-α and IFN-γ are the major inflammatory cytokines secreted by immune cells activated by PHA, they are also located in the tumor microenvironment." (PMID 23761816, 2013). "Metronomic gemcitabine also significantly increased apoptosis in cancer-associated fibroblasts and induced greater reductions in the tumour levels of multiple pro-angiogenic factors, including EGF, IL-1α, IL-8, ICAM-1, and VCAM-1." (PMID 20531411, 2010). "In two-stage skin carcinogenesis, EP2 null mice have lower tumor incidence and fewer tumors/mouse along with reduced TPA-induced epidermal hyperplasia, inflammatory cell infiltration, IL-1α expression and lower cAMP levels than wild-type mice." (PMID 21297902, 2010). "These factors, including TNF-α, IL-1α, IL-1β, VEGF, and fibroblast growth factor 2 (FGF-2), raise leptin levels and promote tumor growth and differentiation." (PMID 19017403, 2008). "IHC staining revealed strong IL-1α expression in basal-like cells at the margins of the differentiated SCC tumor nests, while keratinized tumor cells distant from the stroma were negative for IL-1α." (PMID 40940885, 2025). "Specifically, TAS-115 alone and in combination with DOXO significantly reduced the levels of key pro-inflammatory cytokines, including TNF-α, IL-1α, and IL-6, which are often elevated in the TME and contribute to tumor progression, therapy resistance, and immunosuppression." (PMID 41289612, 2025). "IHC staining was performed for eight cytokine proteins—TNF-α, IFN-γ, TGF-β1, IL-1α, IL-1β, IL-2, IL-6, and IL-12—in paired PeCa tumour samples and corresponding negative-margin tissue." (PMID 41465261, 2025). "Cytokine expression analysis revealed upregulation of IL-1α, IL-2, IL-4, and TNFα and downregulation of IL-6 and IL-8 in JX14P TAMs compared to JX14P-RT TAMs, suggesting that JX14P-RT TAMs have a higher capacity for tumor-promoting inflammation." (PMID 40386422, 2025). "Furthermore, NF-κB can be additionally activated by an IL-1α feedback loop, leading to increased levels of hyaluronic acid in the GBM microenvironment, which promotes tumor invasion." (PMID 40497976, 2025). "Previous studies suggested that IκBζ target genes, such as IL1A, IL1B, or IL6, promote tumor cell proliferation, although it is unclear whether these cytokines are predominantly produced by the tumor cells or the surrounding TME19–21." (PMID 40562773, 2025). "Anti-IL-1α treatment resulted in a moderate attenuation of tumor growth, with no significant reduction in mortality." (PMID 38612760, 2024).
tumor (continued). "Among them, IL-1α, IL1RAP, IL18RAP, and SIGIRR may affect the prognosis of patients by affecting local CD8+ T cell infiltration in the tumor." (PMID 39461030, 2024). "No tumor growth was observed following 4T1 IL-1α KO cell injection in IL-1α KO mice, while tumor development induced by 4T1/WT cells was significantly attenuated." (PMID 38612760, 2024). "In addition, our results show that both tumor- and the TME-derived IL-1α contribute to the progression of TNBC in mice." (PMID 38612760, 2024). "We observed some retardation of tumor growth only in mice that received adoptive transfer of spleen cells from 4T1 IL-1α KO tumor-bearing BALB/c mice, but not from NSG mice." (PMID 38612760, 2024). "However, the TME of IL-1α KO tumors showed higher expression of CXCR3 ligands, such as CXCL9/10, which can attract anti-tumor CXCR3+ CTL, and Th1 lymphocytes, and NK cells." (PMID 38612760, 2024). "LMP1-mediated induction of the NF-κB pathway may result in the activation of IL-1α and IL-1β promotors, and the ample production of IL-1α and IL-1β may facilitate lymphocyte infiltration of an NPC tumour." (PMID 38675906, 2024). "Similarly, we demonstrated the sufficiency of Il1a and Osm combination treatment in Chil1 induction in mouse primary BCC tumor-derived organoids ex vivo." (PMID 39289380, 2024). "This article explores the targets that affect local CD8+ T-cell infiltration in tumors and subsequently affect patient prognosis (IL-1A, IL1RAP, IL18RAP, SIGIRR), which may also become a breakthrough in improving tumor treatment efficacy." (PMID 39461030, 2024). "Activated B cells are known to secrete inflammatory cytokines such as IL-6, Il-1α, TNF-α and Il-1β itself, which may stimulate IL-β secretion and NfκB activation in tumor cells." (PMID 39801513, 2024). "Notably, AOC3, F8, and IL1A were found to be highly expressed in the normal group, while COA6, FKBP4, and LOXL2 were highly expressed in the tumours." (PMID 38577594, 2024). "While IL-1α KO tumors contained lower levels of chemokines, such as CCL2 and CXCL1/2/3, known to attract MDSCs into the tumor, they showed higher expression of CCL5, CXCL9/10, which could attract T lymphocytes and NK cells." (PMID 38612760, 2024). "Finally, analysis of common SASP markers in tumor tissues demonstrated that ADR markedly stimulated the expression of IL-6, IL-1β, and IL-1α, while TC significantly inhibited their expressions." (PMID 39364046, 2024). "Collectively, these results indicate that IL1α, IL1β and IL8 are necessary for 231‐GFP cells to interact with macrophages and subsequently gain the abilities of tumor growth, cancer metastasis, and macrophage infiltration of the tumor sites." (PMID 37551997, 2023). "However, the release of various DAMPs, including ATP, HMGB1 and IL-1α, from dead tumor cells activates the NLRP3 inflammasome in DCs, which can lead to resistance to chemotherapy and promote tumor growth." (PMID 37497237, 2023). "The results showed that reducing the expression of IL1α or IL8 significantly reduced the tumor size of the 231‐GFP cells co‐cultured with THP1‐tdT macrophages by 57% and 67%, respectively, and decreased the tumor weight by 53% and 65%, respectively." (PMID 37551997, 2023). "Collectively, we proposed that within the tumor microenvironment, some early activated TNBC cells will interact with macrophages to elevate the levels of ROS, which activate the ERK1/2‐c‐Jun and NF‐κB signaling pathways to increase the expression of IL1α." (PMID 37551997, 2023). "Skin KS had higher IL-6 and IL-10 gene expression compared to normal tissue, whereas GI KS had higher IL-1A expression." (PMID 37740179, 2023). "These pathways further increase the expression of IL1α, IL1β and IL8 to increase the survival of TNBC when they interact with macrophages, and enhance the tumor growth, metastasis of TNBC, and macrophage infiltration into tumor sites." (PMID 37551997, 2023).
tumor (continued). "IL-1α in bladder cancer cell CM induces the release of IL-8, HGF, MMP-2, GM-CSF and monocyte chemotactic protein (MCP)-1 by CAFs, which, in turn, reciprocally induce migration and invasion in the tumor cells through MCP and HGF." (PMID 37046676, 2023). "Together, these data warrant future studies addressing whether disruption of the local IL-1α/TNFα axis can impede EMH and how cell products of EMH induced by IL-1α and LIF impact the tumor microenvironment and cancer outcomes." (PMID 37134077, 2023). "Considering the results of gene expression microarray analysis in our previous study, we selected IL-1α, IL-1β, CXCL1, and IL-8 as candidates that may be responsible for tumor-induced osteoclastogenesis (red bars)." (PMID 36614130, 2022). "It has been shown that abnormally high LIF expression in the tumor microenvironment can promote macrophage aggregation, which could secrete IL6 and IL-1α to induce muscle atrophy and cachexia." (PMID 35740622, 2022). "Activated M1 macrophages typically express CD40 and CD86 and secrete higher levels of proinflammatory factors than M2 macrophages, such as IL-1α, tumor necrosis factor (TNF), and IL-12, which mainly exert an antitumor immune response and directly kill tumor cells in the early stage of a tumor." (PMID 35740975, 2022). "In the current study, we found that many of IL1 signaling molecules (e.g., IL1α, IL1β, IL1R1, IL1RAP, IL36, IL36R and IRAKs) were highly activated during KSHV infection or in KSHV+ tumor cells and tissues, indicating the crucial role of these molecules functions in KSHV pathogenesis and oncogenesis." (PMID 36457850, 2022). "Regardless of tumor type, patients with values of sTIM3, IFNα, IFNγ, IL1β, IL1α, IL12p70, MIP1β, IL13, sCD28, sGITR, sPDL1, IL10 and TNFα below the median had longer overall survival (p<0.05)." (PMID 36405727, 2022). "Additionally, in response to TSLP, tumor cells have been shown to be secreting IL-1α that act on myeloid cells in the TME, which subsequently secrete TSLP back to tumor cells, creating an IL-1α/TSLP positive feedback loop." (PMID 36467403, 2022). "In addition to thrombin-mediated cleavage of fibrinogen and PAR-1, it is important to note that thrombin cleaves various other substrates that influence the anti-tumor immune function such as FXIII, IL-1α, osteopontin, and the complementary factors." (PMID 35406450, 2022). "Likewise, increased expression of IL1A (log2 fold change = −4.15) and TGFA (log2 fold change = −2.28) was observed in the HCC tumor cells leading to increased expression of TME-derived MMP9 and MMP2, respectively." (PMID 33995488, 2021). "BC cell-derived IL-1α also induces expression of TSLP from tumor infiltrating myeloid cells, and TSLP, in turn, induces expression of B cell lymphoma-2 (Bcl-2) in tumor cells, promotes tumor cell survival, and skews the TME toward Th2 inflammation, sustaining lung metastatic survival." (PMID 34602858, 2021). "Our in vitro study showed that hypoxic stress did not induce IL1A or IL6 expression in tumor cells or macrophages but dramatically enhanced their expression when co-cultured with tumor cells." (PMID 34362882, 2021). "Studies have found that IL-1α is a marker of tumor cells released into the circulation rather than into the lymphatic system." (PMID 34602858, 2021). "In addition, the miR-126 inhibitor obviously decreased the ratio of CD44+ CD90+ CD133+ cells, as well as the levels of IL-1α, SRY, Oct4, IL-6, and TGF-β in tumor tissues of mice." (PMID 34746322, 2021). "Generally, chemotherapy or environmental stresses like hypoxia can promote TAMs to overexpress IL-8 and its receptors, while tumor cells could also be stimulated to secrete IL-8 after NF-κB is activated by TNF-α and IL-1α." (PMID 34625124, 2021). "In addition, LTB, IL1A, LY9, and SLAMF7 were differentially expressed between normal and tumour tissues." (PMID 33397394, 2021).